SMAD6 (SMAD family member 6)
Diseases named in the same sentence as SMAD6 in open-access papers (continued):
Sharing a sentence is not in itself a finding about the gene and the disease.
cancer (22 papers, 2011 to 2025). A tumor composed of atypical neoplastic, often pleomorphic cells that invade other tissues. "Fluorescent labeled MDA-MB-231 cells have been microinjected into Tg (fli1:EGFP) zebrafish embryos and used to show that Smad6 and Bmp6 expression regulates cancer cell invasion and is linked to E-cadherin expression." (PMID 37048068, 2023). "This patient was identified to have a missense VUS with a high score of pathogenic prediction in the ERCC6L2 and SIK3 cancer-related genes in addition to VUS in the SMAD6 CRC-related gene." (PMID 36077770, 2022). "In pan-cancer analysis, SMAD6 exhibits differential expression between various cancers and normal tissues, suggesting its potential role in multiple cancers warrants further investigation." (PMID 38767747, 2024). "The role of the G2M checkpoint is to prevent cells with genomic DNA damage from entering the mitotic phase, indicating that cancer cells with low SMAD6 expression exhibit more severe DNA damage and greater genomic mutation diversity." (PMID 38767747, 2024). "Integrating single-cell and pan-cancer transcriptome data, we analyzed the potential role of SMAD6 in various cancers, including BCa, revealing that lower expression of SMAD6 in BCa is associated with a worse prognosis." (PMID 38767747, 2024). "Some of the high scoring BioChIP-seq enrichment sites included genes that have been implicated in cancer metastases (DDR1, BMP4, and SMAD6), and cell cycle and survival (CDIP1 and PPP2R5A)." (PMID 36207293, 2022). "SMAD family member 6 (SMAD6) has been reported in the initiation and progression of human cancers by acting as a biological participant." (PMID 31992960, 2020). "The functional linkage between SMAD6 and cancer most likely impacts cancer initiation and progression, because SMAD6 expression is deregulated in cancers." (PMID 29352111, 2018). "SMAD6, which is downstream of ALK2, inhibits EMT in endocardial cells underlining the importance of SMAD6 in cancer development." (PMID 22685544, 2012). "SMAD6: rs4147407 was located in the second level of the tree structure and was shown to interact with the INHBC: rs2228225 to influence cancer risk." (PMID 21984931, 2011). "I-Smads (Smad6 and Smad7) are of key importance for maintaining a proper physiological response to TGF-β and BMP signaling and their deregulation has been linked to a number of different diseases, including fibrosis and cancer." (PMID 38876303, 2024). "Survival analysis demonstrated that the role of SMAD6 varies in different cancers." (PMID 38767747, 2024). "Simultaneously, we also analyzed the role of SMAD6 in various cancers." (PMID 38767747, 2024). "The present study demonstrates that R81 methylation also plays roles in Smad6-mediated inhibition of osteogenic differentiation, as well as Smad6-mediated stimulation of cellular invasiveness, a function recently assigned to Smad6 with implications in multiple types of cancers." (PMID 33667543, 2021). "SMAD6 has been reported to participate in initiation and progression of many human cancers." (PMID 31992960, 2020). "SMAD6 has been unmasked as an important regulator in a variety of human cancers." (PMID 31992960, 2020). "Literature has reported that SMAD6 acts as a downstream target of miRNA to regulate the TGF-β signaling pathway, thereby further inhibiting cancer cell proliferation." (PMID 38767747, 2024). "Based on metabolism landscape results, SMAD6 likely upregulates methionine metabolism in cancer cells by mediating the TGF-β signaling pathway, leading to cisplatin resistance in cancer cells." (PMID 38767747, 2024). "RCC tissues that successfully generated organoids highly expressed genes associated with stemness (WNT6/11, FZD8/9 and JAG2), cell matrix (MMP2, COL1A1), fatty metabolism (ACOT2, LIPE) and cancer development (TGFB1, SMAD6/7, EGF and FGF1)." (PMID 35802820, 2022).
cancer (continued). "Although the Ring construct exhibits its protection on PIAS3 only with excessive nuclear-Smad6 expression, it triggers a reduction of endogenous PIAS3 in native GBM cells and thus demonstrates a cancer-promoting function." (PMID 29950561, 2018). "We found two major types of complexes that are affected by miRNAs during cancer progression; the first contains SMAD3, SMAD2, SMAD4, SMAD6, FOXO1, HOXC8, and SKIL, which are connected to AKT1, which is in turn a key modulator of TGF-B signaling pathway." (PMID 24391925, 2013). "Notably, SMAD6 mRNA colocalized less with YTHDC1 in tumoral tissues than in paratumoral tissues, indicating disrupted binding during cancer progression." (PMID 39741187, 2025). "If not inhibited by endogenous (e.g., Smad6 and Smad7) or pharmacological (e.g., galunisertib or SB-431542) agents, increased TGF-β-Smad2/3 signaling activity in cancer cells induce cancer cell migration and invasion." (PMID 39724753, 2024).
infection (8 papers, 2006 to 2023). The state of being infected such as from the introduction of a foreign agent such as serum, vaccine, antigenic substance or organism. "As we would have predicted, treatment of iPSCs with LDN, conditions in which iPSCs become able to allow IE gene expression after infection, also led to a decrease in SMAD6 mRNA expression." (PMID 34061599, 2021). "In Mtb-infected/Fe-supplemented rabbits, expression of IFNG, TNFA, and IL1B was significantly down-regulated, whereas expression of IL6 and SMAD6 was up-regulated, compared to placebo-treated animals, at 4 weeks post-infection." (PMID 31382404, 2019). "At 8 weeks post-infection, expression of SMAD6 and SMAD7 was significantly up-regulated in the Mtb-infected/Fe-supplemented animals, compared to placebo-treated rabbits." (PMID 31382404, 2019). "Our study revealed that the infection with the active form of AMPK progressively reduced phosphorylation of Smad1/5 induced by BMP6, concomitant with elevation of Smad6." (PMID 33169942, 2020). "Moreover, at least five transcription factors, such as the oncogene MYB, SMAD family members 6 and 9 (SMAD6 and SMAD9), and histone decetylase 5 (HDAC5), were significantly affected by infection in CHB." (PMID 27197554, 2016). "Interestingly, SMAD6 and KEN1, negative regulators of the transforming growth factors (TGF)-β and the JAK/STAT pathway, respectively, were both suppressed following VSNJV infection in W8 cells." (PMID 37896885, 2023).
cardiovascular disease (2 papers, 2022 to 2024). "Taken together, carrying a pathogenic SMAD6 might be insufficient to definitively cause cardiovascular disease in all cases, and, as such, more research is required to identify the missing information, and to understand how it contributes to disease." (PMID 36414630, 2022). "A genetic test is best offered to family members of SMAD6 variant-positive patients with cardiovascular disease or RUS as some clinical overlap with the cardiovascular disease might exist." (PMID 36414630, 2022). "Hence, no clinical overlap of a variant-positive SMAD6 carrier with cardiovascular disease or CRS with any abnormality affecting the other organ systems has been observed to date." (PMID 36414630, 2022). "A SMAD6 genetic uptake of 4.6% was reached in more severely affected BAV-related aortopathy patients, i.e., BAV patients who underwent surgical repair for aneurysmal disease before the age of 50, and with a positive family history for cardiovascular disease." (PMID 36414630, 2022).
genetic disorders (2 papers, 2022 to 2025). "Nonetheless, in the upcoming years we will confidently identify the SMAD6-related molecular patterns associated with these three distinctive genetic disorders." (PMID 36414630, 2022). "With this review, we provide a comprehensive overview on SMAD6-deficiency in human genetic disorders by summarising the clinical, (patho)genetic and cellular (dis)similarities observed in human and mouse models." (PMID 36414630, 2022). "In summary, three distinctive human genetic disorders are caused by SMAD6 deficiency without domain-specific or mutation-type genotype–phenotype correlation making proper patient management difficult." (PMID 36414630, 2022).
heart disease (1 paper, 2025). "All four CHD-APAH patients with SMAD6 variants had a complex form of heart disease." (PMID 40133303, 2025).
skeletal dysplasia (1 paper, 2020). Any Mendelian diseases that affects growth and development of the skeleton. "We are only aware of one other skeletal dysplasia reported in association with an inhibitory SMAD (which include SMAD6 and SMAD7)." (PMID 31525280, 2020).
SMAD6 also shares sentences with these, for which no sentence is quoted: aortic coarctation (2 papers); colon cancer (2); embryonal carcinoma (2); fibrosis (2); adenocarcinoma (1); aortic valve calcification (1); Cachexia (1); Choreoathetosis (1); Chronic Hepatitis C (1); colon adenocarcinoma (1); dilated cardiomyopathy (1); endometriosis (1); endothelial dysfunction (1); holoprosencephaly 9 (1); Hypertension (1); hypothyroidism (1); kidney cancer (1); larynx cancer (1); lymphoma (1); microcephaly (1); Neonatal respiratory distress (1); neurodevelopmental disorder (1); neurological diseases (1); ovarian adenocarcinoma (1); parasitemia (1); Patent foramen ovale (1); Pitt-Hopkins syndrome (1); pulmonary hypertension (1); Sagittal craniosynostosis (1); schistosomiasis (1).
A further 6 diseases each share a sentence with SMAD6 in 1 paper.